CDCA3 (cell division cycle associated 3)
Description:
F-box-like protein which is required for entry into mitosis. Acts by participating in E3 ligase complexes that mediate the ubiquitination and degradation of WEE1 kinase at G2/M phase (By similarity).
Synonyms: TOME-1; GRCC8; TOME1
Tractability: PROTAC: UniProt records ubiquitination sites on it; ubiquitination databases record sites on it.
Safety:
Unwanted effects reported when the protein is acted on. In parentheses: how it was acted on, where the effect was seen, and who reports it.
diabetes mellitus (source: ClinPGx)
increase in pulse rate (source: ClinPGx)
less of an increase in pulse rate (source: ClinPGx)
weight gain (source: ClinPGx)
Gene: Protein-coding gene on chromosome 12 (6,844,793 to 6,851,318, reverse strand). Ensembl gene ENSG00000111665.
Subcellular location: Cytoplasm, cytosol
Subcellular location (Human Protein Atlas): Cytosol
Gene Ontology:
Molecular function: protein binding
Biological process: protein ubiquitination
Cellular component: adherens junction; cytosol
Genetic constraint (gnomAD): Loss-of-function variants: 14 observed, 24.74 expected, observed/expected ratio (o/e) 0.57, 90% interval 0.37 to 0.88. The synonymous counts are far from expectation, so gnomAD's model fits this gene poorly and the ratio says little. Missense variants: 258 observed, 303.34 expected, observed/expected ratio (o/e) 0.85, 90% interval 0.77 to 0.94. Synonymous variants: 76 observed, 116.52 expected, observed/expected ratio (o/e) 0.65, 90% interval 0.54 to 0.79.
Homologues: Orthologues: chimpanzee CDCA3 (99% identical), macaque CDCA3 (99% identical), dog CDCA3 (84% identical), pig CDCA3 (82% identical), rabbit CDCA3 (82% identical), guinea pig CDCA3 (78% identical), rat Cdca3 (74% identical), mouse Cdca3 (73% identical), zebrafish cdca3 (30% identical), Drosophila melanogaster msb1l (21% identical).
Diseases named in the same sentence as CDCA3 in open-access papers:
CDCA3 is named in the same sentence as 80 diseases in open-access papers, as found by Europe PMC text mining. Sharing a sentence is not in itself a finding about the gene and the disease. The quoted sentences say what the papers report.
breast carcinoma (15 papers, 2013 to 2025). "For instance, CDCA3 has been implicated in promoting proliferation and metastasis in breast cancer by regulating the cell cycle, while CDCA5 has been shown to enhance chemoresistance and tumor growth in ovarian cancer." (PMID 39924497, 2025). "For example, in breast cancer cell lines and renal cell carcinoma, upregulated CDCA3 levels was associated with doxorubicin and sunitinib resistance, respectively." (PMID 34572879, 2021). "According to the data from TCGA, CDCA3 expression was up-regulated and associated with a worse prognosis in breast cancer." (PMID 32944002, 2020). "CDCA3 expression affects other cancers as well, such as renal cell carcinoma, breast cancer, acute myeloid leukemia, and non-small-cell lung cancer." (PMID 33604380, 2021). "Several other studies have also shown that CDCA3 plays a significant role in the occurrence and development of tumors, including non-small cell lung cancer, prostate cancer, breast cancer, and KIRC." (PMID 34905505, 2021). "CDCA3 is overexpressed in bladder cancer and is related to prognosis and its high expression is closely related to survival in breast cancer." (PMID 34905505, 2021). "In breast cancer, CDCA3 expression was found to be up-regulated and correlated with an unfavorable prognosis." (PMID 32944002, 2020). "A survival analysis of breast cancer patients with an overexpression of CDCA3 showed poor prognosis (HR = 1.59)." (PMID 29467944, 2018). "A high expression of CDCA3 was highly correlated with patient survival under all breast cancer subtypes, with an HR of 1.59." (PMID 29467944, 2018). "The highest mRNA expression of CDCA3 in breast cancer tumors was in the basal breast cancer patients." (PMID 29467944, 2018). "In the current analysis, CDCA3 expression levels were high in invasive ductal breast carcinoma and were highly correlated with a low survival probability for breast cancer patients, leading to a poor prognosis." (PMID 29467944, 2018). "By analyzing the various tumor subtypes and cell lines of breast cancer, we found evidence for CDCA3, CDCA5, and CDCA8 involvement in breast cancer, resulting in an overall poor prognosis." (PMID 29467944, 2018). "In ER-positive, luminal A, and luminal B subtypes, the high expression of CDCA3 dramatically reduced the survival period for breast cancer patients." (PMID 29467944, 2018). "Neve dataset analysis of breast cancer cell lines showed the expression of CDCA3, and intensity percentile for each cell line." (PMID 29467944, 2018). "And CDCA3 was associated with worse RFS and OS in Luminal A breast cancer." (PMID 34384030, 2021). "Moreover, it has been reported that CDCA3 expression is related to prognosis for bladder cancer cases and luminal A breast cancer." (PMID 32104702, 2020). "The collective evidence suggested that CDCA3 exerted tumor-promoting action in breast cancer." (PMID 32944002, 2020). "In addition, the survival analyses revealed that the expression of CDCA3 in many breast cancer subtypes highly correlated with bad prognoses." (PMID 29467944, 2018). "Moreover, besides exerting a cycle-regulating effect, CDCA3 could contribute to chemoresistance in breast cancer and renal cell carcinoma." (PMID 33980246, 2021). "While other molecular functions for CDCA3 are yet to be determined, there are also emerging roles for CDCA3 in solid malignancies; upregulated CDCA3 expression has been noted in liver cancer, gastric cancer, colon cancer, oral squamous cell carcinoma, and breast cancer." (PMID 34572879, 2021). "In short, CDCA3 could be considered as a potential target for these breast cancer subtypes." (PMID 29467944, 2018). "According to the results, we found that the high expression of CDCA3 was correlated with the poor prognosis in HCC, breast cancer, and lung cancer (HR > 1, p < 0.05)." (PMID 33604380, 2021). "CDCA3, CDCA5, and CDCA8 are overexpressed and function as oncogenes in HCC and gastric and breast cancer." (PMID 34660326, 2021).
breast carcinoma (continued). "In a similar expression pattern to CDCA3 and CDCA5, a high expression level of CDCA8 also correlated with a bad prognosis for breast cancer patients with a shorter RFS." (PMID 29467944, 2018). "Moreover, for reconfirmation, we downloaded the expression profiles of 33 human cancers (including liver cancer, breast cancer, colon cancer and so on) from the UCSC Xena database and comprehensively analyzed the mRNA level of CDCA3 in various human cancers." (PMID 33980246, 2021). "High expression of CDCA3 and CDCA8 had been found in breast cancer, resulting in a poor prognosis." (PMID 34053447, 2021). "The CDCA4 mRNA expression level in breast cancer subtypes was not as high as that of the CDCA3 level." (PMID 29467944, 2018). "Altogether, these findings suggested CDCA3, CDCA5, and CDCA8 could have a high potency as targeted breast cancer therapies." (PMID 29467944, 2018).
hepatocellular carcinoma (13 papers, 2019 to 2024). A malignant tumor that arises from hepatocytes. "In hepatocellular carcinoma, E2F4 promotes the proliferation, migration and invasion of hepatocellular carcinoma cells by upregulating CDCA3." (PMID 37349788, 2023). "It has been reported that CDCA3 is closely related to immune infiltration in hepatocellular carcinoma." (PMID 36213833, 2022). "We analyzed the relationship between the expression of CDCA3 and prognosis of patients with hepatocellular carcinoma (HCC) using the Kaplan–Meier plotter database and Gene Expression Profiling Interactive Analysis (GEPIA)." (PMID 33604380, 2021). "E2F4 promotes proliferation and cell cycle progression in hepatocellular carcinoma cells by up-regulating CDCA3 expression." (PMID 34905505, 2021). "Based on the TIMER database, Wang found that CDCA3 is related to the infiltration of many immune cells in hepatocellular carcinoma." (PMID 34905505, 2021). "In conclusion, our findings suggested that CDCA2, CDCA3, CDCA4, CDCA5, and CDCA8 might have potential diagnostic and prognostic values for hepatocellular carcinoma." (PMID 32913466, 2020). "Genes, such as CDCA3, KIF15, and TCF19, are linked with the proliferation of various cancer cells, such as oral cancer, pancreatic cancer, and hepatocellular carcinoma cells, but these genes may be responsible for the proliferation of BRCA cells." (PMID 31311202, 2019). "CDCA3 controls the G1 phase, which acts as one of the prognostic genes for hepatocellular carcinoma (HCC) and is also involved in LC cell proliferation, migration, invasion, and apoptosis, as well as CRC cell proliferation." (PMID 32104702, 2020). "The role of these genes (UBE2T, CDCA3, and CDCA5) in the progression of hepatitis, cirrhosis and hepatocellular carcinoma remains to be further investigated." (PMID 38890649, 2024). "Our results indicated that a panel of E2F target gene signature, comprising of HN1, KIF4A, CDCA3, CDCA8 and SSRP1, is a reliable tool for predicting the overall survival of Hepatocellular carcinoma patients, and provided significant reference of clinical risk for Hepatocellular carcinoma patients." (PMID 35591857, 2022). "An analysis of various tumors and the paired paracancerous tissues in TCGA showed that the expression of CDCA3 in bladder urothelial carcinoma, KIRP, hepatocellular carcinoma and other cancers was significantly higher than those in corresponding paracancerous tissues." (PMID 34905505, 2021). "In conclusion, we supposed that CDCA2, CDCA3, CDCA4, CDCA5 and CDCA8 might be oncogenes in hepatocellular carcinoma." (PMID 32913466, 2020). "CDCA3 and CDCA5 had been considered as potential oncogenes in hepatocellular carcinoma." (PMID 32913466, 2020). "In Wurmbach's dataset 20, CDCA2, CDCA3, CDCA4, CDCA5 and CDCA8 were up-regulated in hepatocellular carcinoma (HCC), with fold changes of 1.813, 3.214, 1.832, 2.422 and 1.693, respectively." (PMID 32913466, 2020).
lung cancer (13 papers, 2020 to 2025). A malignant neoplasm involving the lung. "For instance, circ_0001421 promotes glycolysis and lung cancer development by regulating miR-4677-3p to upregulating cell division cycle associated 3 (CDCA3)." (PMID 35365168, 2022). "We provide evidence that CDCA3 levels are increased in EGFR mutant lung cancer and these levels are associated with sensitivity to TKIs." (PMID 34572879, 2021). "The aim of our study was to determine whether the protein cell division cycle-associated protein 3 (CDCA3) might be a biomarker for TKI response in EGFR mutant lung cancer." (PMID 34572879, 2021). "Expression of CDCA3 is a prognostic factor and potential novel therapeutic target in non–small cell lung cancer." (PMID 38994368, 2024). "We have demonstrated in non‐small cell lung cancer (NSCLC) the role of CDCA3 in mediating efficient G2/M progression, tumor cell proliferation, where depleting this protein induces senescence." (PMID 36691744, 2023). "It had been found that CDCA3 was significantly illustrated in the lung cancer samples and correlated with clinical progress." (PMID 34384030, 2021). "It has been reported that CDCA3 is significantly upregulated in lung cancer, the deletion of CDCA3 gene inhibits the proliferation of lung adenocarcinoma cell lines and promotes cell senescence, which is consistent with our results." (PMID 34430085, 2021). "Our previous work has demonstrated that CDCA3 is a marker of chemotherapy sensitivity in lung cancer." (PMID 34572879, 2021). "CDCA3 expression correlates with immune exhaustion markers such as PD-1 and CTLA-4, and is associated with increased immune infiltration and poor outcomes in renal and lung cancers." (PMID 40963614, 2025). "Recently, it has been reported that CDCA3 is regulated by miR-144-5p in lung cancer cells." (PMID 39337462, 2024). "In addition, increasing the levels of CDCA3 enhances TKI sensitivity in models of TKI-resistant EGFR mutant lung cancer." (PMID 34572879, 2021). "What’s more, direct evidence for CDCA3 in lung cancer has also been provided." (PMID 34430085, 2021). "Our findings propose that strategies to upregulate CDCA3 levels might improve TKI response in EGFR mutant lung cancer." (PMID 34572879, 2021). "The gene CDCA3 (cg27042065 located) is also associated with lung cancer and survival of cancer patients, and Song and Yang (2018) have reported that gene LOC338797 (cg26387355 located) is related with progression of tumor in lung cancer patients." (PMID 32302299, 2020). "Among these genes, the expression of two genes (CDCA3: p = 0.0002 and FAM111B: p = 0.0004) had a significant impact on the prognosis of lung cancer patients." (PMID 39337462, 2024).
bladder cancer (12 papers, 2014 to 2025). "Specifically, MYBL2 contributes to the proliferation and metastasis of bladder cancer by upregulating the expression of cell division cycle-associated protein 3 (CDCA3)." (PMID 38725627, 2024). "LINC00707 serves as a ceRNA to combine with miR-145 and thus affect CDCA3 expression and decrease the apoptotic cell number of bladder cancer UMUC3 and T24T cells." (PMID 35155429, 2022). "We also found the bona fide driver of melanoma metastasis and invasion NEDD9 as well as DEPDC1 and CDCA3, genes involved in progression of bladder cancer or enhanced proliferation." (PMID 24799129, 2014). "Besides, it was also revealed that LMNB2 expression was upregulated in human bladder cancer tissues, and it promoted the proliferation of bladder cancer cells via transcriptional activation of CDCA3 expression." (PMID 40366008, 2025). "Cumulative studies indicate that CDCA3 is abnormally high expressed in multiple human malignancies, such as glioma, prostate cancer, pan-renal cell carcinoma, and bladder cancer, which may contribute to tumor progression as an oncogene." (PMID 40822457, 2025). "CDCA3, ANLN, STMN1, and DHCR24 play important roles in cell proliferation and migration of bladder cancer." (PMID 39540204, 2024). "In bladder cancer, LINC00707 is involved in Wnt/β-catenin signaling to contribute to the proliferation of UMUC3 and T24T cells, through sponging miR-145 to modulate CDCA3 expression." (PMID 35155429, 2022). "In vitro bladder cancer assays revealed LINC00707 knockdown leads to damaged premetastatic abilities of UMUC3 and T24T cells via targeting miR-145 and further inhibition of CDCA3 expression." (PMID 35155429, 2022). "Levels of CDCA3, CENPF, CENPA and KIF4A are correlated in bladder cancer." (PMID 34905505, 2021).
gastric cancer (12 papers, 2020 to 2023). A primary or metastatic malignant neoplasm involving the stomach. "Recent studies have shown that CDCA3 functions as a crucial oncogene and is associated with poor outcomes in patients with gastric cancer, and it is a potential therapeutic target in the management of gastric cancer." (PMID 33604380, 2021). "As revealed by PPS (HR = 0.67, 95%CI = 0.54–0.84, p = 0.00038), the high CDCA3 expression was associated with the better prognosis in gastric cancer because the HR < 1 and p < 0.05." (PMID 33604380, 2021). "CDCA3 expression is increased in gastric cancer cells and is associated with a poor prognosis." (PMID 34905505, 2021). "CDCA3 overexpression in vivo and in vitro promotes the growth and colony formation ability of gastric cancer cells, while inhibiting CDCA3 expression mitigates these effects." (PMID 34905505, 2021). "CDCA3 has been shown to promote cell proliferation and invasion through activation of the Ras signaling pathway or hypomethylation in gastric cancer cells." (PMID 33778011, 2021). "CDCA3 promotes cell proliferation by activating the NF-κB/cyclin D1 axis in colon cancer, which is probably a potential prognostic biomarker in gastric cancer." (PMID 34699322, 2021). "CDCA3, a cell division cycle protein, promoted the proliferation and cell cycle progression of colorectal and gastric cancer cells." (PMID 34335934, 2021). "Knockdown of SP1 downregulated CDCA3 expression, and the proliferation and invasion of gastric cancer cells is significantly inhibited." (PMID 34905505, 2021). "Cell division cycle associated protein-3 (CDCA3) modulates cell cycle processes, also called as trigger of mitosis entry 1, and it was identified to play a pro-carcinogenic role in gastric cancer, colorectal cancer and acute myeloid leukemia." (PMID 33109222, 2020). "CDCA3 has been widely reported as a prognostic marker for gastric cancer." (PMID 37340405, 2023). "Suppression of CDCA3 decreased cell proliferative, healing, or invasive ability in gastric cancer." (PMID 32944002, 2020). "Cell division cycle-associated protein-3 (CDCA3) is frequently upregulated in the tumor tissues and is associated with oncogenic properties in several cancers, such as colorectal, prostate, non-small-cell lung, and gastric cancers; however, its role in the pathogenesis of HCC is unknown." (PMID 33604380, 2021). "CDCA3, through regulation by specificity protein 1 (SP1) and hypomethylation of its gene body, affects gastric cancer (GC) cell proliferation and invasion." (PMID 32716971, 2020). "Furthermore, in gastric cancer CDCA3 expression is regulated by DNA methylation, and the binding activity of SP1 and the CDCA3 promoter is significantly up-regulated." (PMID 34905505, 2021).
colorectal cancer (11 papers, 2020 to 2024). A primary or metastatic malignant neoplasm that affects the colon or rectum. "For example, miR-145-5p suppresses the proliferative rate, the metastasis and EMT of colorectal cancer cells by negatively regulating CDCA3." (PMID 39039505, 2024). "CDCA3 overexpression has been reported to promote the G1/S phase transformation and promote the proliferation of colorectal cancer cells by activating the NF-kB/cyclin D1 signaling pathway." (PMID 34239875, 2021). "CDCA3 overexperssion promotes the proliferation of colorectal cancer cells, while knocking down CDCA3 expression in vivo and in vitro decreases the proliferation of colorectal cancer cells." (PMID 34905505, 2021). "For example, in colorectal cancer, CDCA3 can mediate p21-dependent proliferation by regulating E2F1 expression or promote cell proliferation by activating the NF-KappaB /cyclin D1 signaling pathway." (PMID 34430085, 2021). "In particular, the inhibition of CDCA3 expression induces cell cycle arrest in colorectal cancer cells, thereby promoting cell apoptosis." (PMID 34905505, 2021). "For example, knockdown of CDCA3 inhibited the growth ability of NCSLC cells via arresting cells in the G2/M phase, while in colorectal cancer, CDCA3 could induce cell cycle arrest in the G1 phase." (PMID 33980246, 2021). "Also, CDCA3 was reported to exert a carcinogenic effect in NSCLC and colorectal cancer via different signaling pathway." (PMID 32944002, 2020).